BECN1 (beclin 1)
Diseases named in the same sentence as BECN1 in open-access papers (continued):
Sharing a sentence is not in itself a finding about the gene and the disease.
cancer (continued). "Since autophagy promotes cancer cell survival at late stages of the disease, the Beclin 1-dependent autophagy activation may contribute to the chemotherapy resistance associated with XIAP and cIAP1 overexpression found in several types of human cancer." (PMID 25669656, 2015). "Thus, the chemotherapy resistance associated with XIAP and cIAP1 overexpression observed in several human cancers may be, at least in part, due to the Beclin 1-dependent autophagy activation by IAPs described in this study." (PMID 25669656, 2015). "We speculate that beclin-1 expression in the stromal cells may be important to maintain the levels of IL-1 and to maintain mesenchymal collagen-binding receptors in the active state in cancer-stromal microenvironments." (PMID 25955408, 2015). "Thus, beclin-1 is a key protein and reliable biomarker of autophagy in various cancers." (PMID 25955408, 2015). "However, evidence supporting a role for autophagy in genome protection in established cancers is limited and the role of Beclin 1, if any, is unknown." (PMID 24956373, 2014). "The mechanism of aberrance of Beclin-1 expression in different types of cancers is largely unknown." (PMID 23578251, 2013). "Thus, it is possible that preferential cleavage sites might be employed to generate different functional Beclin 1 fragments depending on cell types and treatments, which may have critical implications for cancer treatment." (PMID 23840208, 2013). "Thus, inactivation of autophagic genes such as Beclin 1 may contribute to the development of human cancers." (PMID 23573264, 2013). "As previous studies demonstrated that gene-virotherapy resulted in an augment expression of transgenes due to replication of the virus within cancer cells, the important question arises: whether integrating Beclin-1 gene therapy into an oncolytic virus elicit strong antileukemia activity?" (PMID 23765161, 2013). "In cancer, it has been shown that autophagy may be an important anti-cancer mechanism in vivo since the expression level of beclin-1, a fundamental gene for autophagy, is inversely correlated with the malignancy of brain tumors and is directly correlated with survival." (PMID 21695150, 2011). "Therefore, it appears that both under- and overexpression of Beclin 1 may exist in human carcinomas." (PMID 20842118, 2010). "Melatonin has been found to inhibit cancer cells by activating autophagy through ULK1 activation, following mTOR inhibition, which phosphorylates Beclin-1." (PMID 40534879, 2025). "Their work demonstrated that USP15 knockout enhanced cancer cell migration and invasion and that USP15 attenuated autophagy through BECN1 deubiquitination." (PMID 40762380, 2025). "The analysis of CNVs in PRKN, OPTN, PINK1, SRC, BNIP3L, BECN1, and MAP1LC3A across various cancer types revealed significant heterogeneity in the types and frequencies of CNVs." (PMID 39859167, 2025). "Further, elevated expression of key autophagy proteins beclin-1, ATG-7, LC-3-I/II, and SQSTM1/p62 reveal that inhibition of autophagy plays a crucial role in regulating DDR capabilities of cancer cells." (PMID 40041432, 2025). "Overall, the Spearman’s correlation coefficients varied across different cancer types, revealing distinct patterns of immune cell correlation with the expression of OPTN, PINK1, MAP1LC3A, PRKN, BNIP3L, BECN1, and SRC." (PMID 39859167, 2025). "In contrast, the overexpression of Beclin-1 can stimulate autophagy and augment ADCD, positioning it as a potential therapeutic target for cancer treatment." (PMID 40710325, 2025).
cancer (continued). "We delved into the molecular mechanisms by which LC3, PINK1, PRKN, SRC, BNIP3L, BECN1, and OPTN regulate mitophagy, cancer progression and drug sensitivity or resistance." (PMID 39859167, 2025). "This is consistent with previous studies in other cancer models, where MCL1 was shown to limit ferroptosis by directly binding and inactivating BECN1." (PMID 41008795, 2025). "The core proteins of the LAP PI3KC3 complex (VPS34, VPS15, BECN1, UVRAG, RUBCN) present potential targets for developing novel cancer therapies." (PMID 39941753, 2025). "Inhibition of mTOR induced autophagy in cancer cells through activation of ULK1, leading to Beclin-1 phosphorylation." (PMID 40756978, 2025). "Last, we gathered the IC50s of a wide variety of drugs among different cancer cell lines through the GDSC and CTRP databases and assessed the relationship between the mRNA values of MAP1LC3A, OPTN, SRC, BNIP3L, BECN1, PINK1, and PRKN and drug sensitivity." (PMID 39859167, 2025). "The regulation of Beclin-1 and ATG2 is essential in the autophagy mechanisms related to cancer treatment." (PMID 39650649, 2024). "Treatment with procaine led to increased transformation of LC3-II and increased expression of autophagy proteins Beclin-1 and ATG5, which in turn triggered apoptosis and autophagy and inhibited the proliferation and differentiation of cancer cells." (PMID 38482052, 2024). "BECLIN-1, through the interaction with BCL-2 protein, also promotes the release of pro-apoptotic molecules, like BAX and BAK in some type of cancer cells." (PMID 39555455, 2024). "Additionally, Beclin-1 and ATGs may serve as predictive indicators in cancer." (PMID 39650649, 2024). "In cancer autophagy, the interaction of Beclin-1 with JAK2 is triggered by IL-6, which allows JAK2 to phosphorylate Beclin-1 at the Y333 site." (PMID 38887520, 2024). "Pterostilbene restores autophagic activity in cisplatin-resistant OSCC cells by activating autophagy-related genes, including ATG5, ATG7, and Beclin-1, through modulation of the AKT pathway, leading to enhanced cancer cell death." (PMID 39840028, 2024). "In rat C6 glioma cells, lidocaine protects the organism from cancer by increasing the transcriptional level of LC3B and Beclin-1 and promoting the formation of cytoprotective autophagy." (PMID 38482052, 2024). "Disrupting the Beclin-1/Bcl2 complex using BH3 mimetics, such as ABT-737, restores autophagic activity and induces cancer cell death." (PMID 39840028, 2024). "Another lncRNA, prostate cancer gene expression marker 1 (PCGEM1), promotes autophagy by increasing the mRNA levels of ATG3, ATG5, ATG12, and Beclin-1." (PMID 36899946, 2023). "IFNγ or CAR-T10%MYXV decreases the activity of AKT, which regulates autophagy through phosphorylating Beclin 1, while overexpression of constitutively active AKT in cancer cells abolishes the antitumor activity of CAR-T10%MYXV and VPS34 level." (PMID 37091978, 2023). "EMT is strongly interconnected with autophagy because both play a vital role in the occurrence and development of cancer and are regulated by various same signaling pathways, such as PI3K/AKT/mTOR, Beclin‐1, and JAK/STAT signaling pathways." (PMID 35676831, 2023). "Changes in ion transport or ion channel activity are enriched in Tat-BECN1-, CAR-T10%MYXV-, or MYXV-treated cancer cells by RNA sequencing." (PMID 37091978, 2023). "Tat-BECN1 and derivatives not only induce autosis specifically in HIV-1-infected cells but also kill cancer cells in culture in vitro and inhibit tumor xenograft growth with negligible systemic toxicity in vivo." (PMID 37091978, 2023). "Western blot results revealed that in both cancer cells, ALA, by upregulating pmTOR expression, reduced the protein content of two autophagy initiation markers, Beclin-1 and MAPLC3." (PMID 38069431, 2023).
cancer (continued). "RGD-N3 (cyclo (Arg-Gly-Asp-d-Phe-Lys(Azide))) can target tumor’s αvβ3 integrin receptor, Beclin 1 derived peptide is a functional peptide that can bind to Class III phosphatidylinositol 3-kinase (PI3KCIII)/Vps34, initiate cancer cell autophagy." (PMID 37919282, 2023). "A previous study reported that p19ARF reduced the formation of the protein complex between BECN1 and its negative regulator, BCL2L1, and then induced autophagy in cancer cells." (PMID 37169793, 2023). "Promising cardiac‐specific biomarkers in cancer‐induced cardiac cachexia models and cachectic cancer patients include factors from the TGF‐β family, such as GDF‐15, autophagy markers, such as Beclin‐1, and markers of protein synthesis, such as AKT and mTOR." (PMID 37654192, 2023). "The study was carried out to investigate the prognostic value of Beclin 1, EGFR and ALK for this cancer." (PMID 36401689, 2022). "Knockdown of genes such as ATG3, ATG5, ATG7, ATG13, and ATG6 (also known as BECN1) inhibited iron uptake and thus ferroptosis in many types of cancer cells." (PMID 35847022, 2022). "Unexpectedly, the data from the CPTAC database, a web resource for analyzing cancer OMICS data, showed that the proteins of BECN1 were dramatically up-regulated in HCC tissue samples compared to in normal tissues." (PMID 36295086, 2022). "ROS can also mediate the induction of autophagy genes, including Beclin-1 or SQSTM1/p62, by regulating the activity of NF-κB in cancer cells." (PMID 35359388, 2022). "Our previous studies also showed that sedanolide and α-phellandrene, which are active components of celery, can increase PI3K, Beclin-1 and LC-3 protein levels, leading to autophagy induction in human colorectal HCT-116 cancer cells and liver J-5 cancer cells." (PMID 34976156, 2022). "Consistent with an overall close correlation between copy number and mRNA expression, the copy numbers of BECN1 and ATG7 correlated significantly with mRNA levels across the entire pan-cancer dataset comprising 9889 patient tumors." (PMID 35681458, 2022). "This pathway has many functions during stress response and cancer development, but MAPKAPK3 is also able to phosphorylate Beclin 1, thereby positively regulating starvation-induced autophagy." (PMID 35454789, 2022). "Increased expression of Beclin-1, XBP1, CHOP, and LC3II in cancer cells suggested the AgNPs-induced mitophagy in cancer cells." (PMID 36365094, 2022). "The interaction between Beclin 1 and MDMX has been preliminarily revealed in a cancer-focused protein–protein interactions network research, without validation." (PMID 36230664, 2022). "MiRNA MIR497 with low expression silenced target genes BECN1, MTDH, and BCL2 to indulge cancer cell differentiation, angiogenesis, and metastasis." (PMID 33802957, 2021). "Further, BECN1 knockdown appears to results in HeLa cell sensitivity to VSV-induced oncolysis, illustrating the role of autophagy in altering cancer cell resistance to oncolytic virotherapy." (PMID 34685652, 2021). "Phosphorylation is considered a key modification of BECN1, and several reports have demonstrated that EGF/EGFR signaling negatively regulates autophagy by directly binding to BECN1 in cancer cells." (PMID 34131122, 2021). "Quantitative analysis of flow cytometry demonstrated that cancer cells treated with PtMet2 and PtMet2–PAMAM markedly upregulated AMPKβ1/2 and Beclin-1 (initiation factors for autophagosome formation) as compared to the control and cisplatin." (PMID 34070401, 2021). "Clinical sample data showed that the level of p-BECN1 (Y333) is related to CRC patient survival and is a predictive marker of a poor cancer prognosis." (PMID 34131122, 2021).
cancer (continued). "Studies have shown that the TRAF6-induced ubiquitination of BECN1 plays a key role in TLR-induced autophagy activation, thereby functionally implicating cancer progression and migration." (PMID 32384667, 2020). "The expression of BECN1 (participates in macrophagy) and PINK1 (participates in mitophagy) was reduced at every stage of cancer development." (PMID 33322704, 2020). "Meanwhile, BECN1 knockdown can inhibit the autophagy degradation of E-cadherin promoted by TRIM29 overexpression and cancer cell metastasis." (PMID 32640423, 2020). "Treatment with FKB+doxorubicin increased the ratio of Beclin-1/Bcl-2, and the ratio of Bax/Bcl-2 in AGS cancer cells indicates that FKB+doxorubicin can increase cell death through pro-apoptotic signaling." (PMID 32882870, 2020). "HepG2 treated with CS3 greatly increased expression of Foxo1 and Beclin-1, confirming the induction of CS3 in cancer cell apoptosis and autophagy." (PMID 31892846, 2020). "Previous studies have shown that in cancer progression, LRPPRC interacts with Beclin 1 and Bcl-2 and forms a ternary complex to maintain Bcl-2 stability, resulting in the maintenance of mitochondrial homeostasis and mitochondrial function." (PMID 32898195, 2020). "When BID is expressed and activated by BSB, Beclin 1 ends up being degraded and autophagy collapses; when BID is not available, Beclin 1 persists and the continuous autophagic flux probably helps cancer cells survive." (PMID 31767857, 2019). "In cancer cells, nuclear p-STAT3-S705 can regulate the transcription of several autophagy-related genes such as BCL2 family members (e.g., BECN1, PIK3C3, CTSB, CTSL, PIK3R1, HIF1A, and BNIP3) and microRNAs with targets of autophagy modulators." (PMID 32565533, 2019). "One study showed that the inhibition of autophagy by silencing of Beclin 1 and ATG5 decreased hypoxia-induced activation of STAT3 and restored cancer cell sensitivity to T-cell cytotoxicity." (PMID 30400561, 2018). "To gain insight into the mechanism by which VP + SF eliminates cancer cells, we evaluated the expression of key proteins involved in apoptosis (PARP, caspase 3, and caspase 9), autophagy (Beclin-1 and p62), and necroptosis (RIP1 and MLKL)." (PMID 29201061, 2017). "With regard to specific 14-3-3 isoforms, there was a report showing that 14-3-3τ up-regulates beclin-1 expression, probably through E2F1, regulating autophagy in cancer cells." (PMID 28404875, 2017). "In this study, we investigated the effect of aspirin on Beclin 1 acetylation and autophagy in CRC cells, providing new insight into aspirin for cancer therapy." (PMID 29088823, 2017). "In cancer cells, the suppression of PI3K/AKT/mTOR pathway and the upregulated protein level of Beclin-1 are consistently connected with the induction of autophagy." (PMID 26808193, 2016). "Expression of Beclin-1 and SIRT1 expression between NNM and cancer tissues was found to be statistically significant (p < 0.001)." (PMID 28070138, 2016). "In our experimental conditions, autophagy played a pro-survival role in cancer cells treated with HMA, given that cell viability decreased, although only partially, when the crucial autophagy regulators Beclin-1 or ATG7 were silenced." (PMID 27816051, 2016). "The results shown in the present study confirm and further extend those of previous reports, showing that beclin-1 and LC3 B-II protein levels are increased in the skeletal muscle of cancer patients." (PMID 27459917, 2016). "First, autophagy was impaired in BECN1 +/− mice and second, BECN1 was downregulated in human breast MCF7 carcinoma cells." (PMID 26862519, 2016). "Beclin 1 and LC3 increased in carcinoma cells following exemestane treatment in 7 (14 %) of 49 patients and 17 (52 %) of 33 patients, respectively." (PMID 26984766, 2016).
cancer (continued). "Beclin 1 maps to a region on chromosome 17q21, and Beclin 1 and UVRAG are monoallelically deleted in certain cancers." (PMID 24956373, 2014). "In the present study, the subcellular localization and expression of Beclin-1 and LC3B proteins in normal cervical squamous epithelial and cancer tissues was detected via QD-IHC." (PMID 25202355, 2014). "Expression of Beclin-1, PCNA, NET-1, Bcl-2, Bax, Survivin in cancer cells and CD34 in stromal microvessels were evaluated immunohistochemically in tissue microarrays comprising 103 cases of HCC and 57 matched adjacent nontumor liver tissues." (PMID 24885292, 2014). "However, the mechanism by which BECN1 modulates cell death in cancer cells remains unclear." (PMID 23833647, 2013). "Recently, the epidermal growth factor receptor antibody cetuximab was found to induce autophagy in cancer cells by downregulating HIF-1α and Bcl-2 and activating the Beclin 1/hVps34 complex." (PMID 23420500, 2013). "Therefore, novel cancer therapeutics may target UVRAG either to increase interaction with Beclin 1 and/or Bif-1, to increase autophagy, and facilitate degradation of oncogenic molecules; or to inhibit the UVRAG-BAX interaction, releasing BAX and triggering apoptosis." (PMID 23840208, 2013). "Beclin 1, Bcl-2, Bcl-xL, Bad and Bax protein expressions were assessed only in the surgical liver tissues from 13 HCC patients (both in the cancer and in the surrounding cirrhotic tissue)." (PMID 22928777, 2012). "Knockdown of 14-3-3 tau inhibited Beclin 1 protein expression and the LC3 puncta in nutrient limited conditions in both the human embryonic kidney HEK293 cells and carcinoma cell line HCT116." (PMID 22761775, 2012). "Studies in different cells lines have shown that cancer cells express lower levels of the autophagy-related proteins LC3-II and Beclin 1 than normal epithelial cells." (PMID 22295229, 2011). "Mechanistically, Beclin 1 interacts with key autophagy-related proteins, including ATG5 and ATG7, to facilitate the formation and maturation of autophagosomes, thereby sustaining cancer cell survival during chemotherapy." (PMID 40843353, 2025). "Indeed, high BECLIN-1 levels correlate both with extended survival of CRC patients and with chemoresistance depending on cancer stages." (PMID 40917756, 2025). "KAT5/TIP60-driven lactylation of PIK3C3/VPS34 at lysine residues 356 and 781 enhances its interaction with BECN1, ATG14, and UVRAG, promoting autophagy that may contribute to cancer progression." (PMID 39979245, 2025). "For instance: FOXO1 is downregulated in CML but shows no significant change in AML or CLL, unlike previous pan-cancer autophagy markers (e.g., BECN1) that lack disease specificity." (PMID 40503228, 2025). "Overall, these findings highlight the complex landscape of CNVs in PRKN, OPTN, PINK1, SRC, BECN1, BNIP3L, and MAP1LC3A across different cancer types, emphasizing the potential impact of these genetic alterations on cancer pathogenesis and the importance of considering CNVs in therapeutic strategies." (PMID 39859167, 2025). "Here, we conduct a comprehensive analysis of a mitophagy-related gene signature, composed of PRKN, PINK1, MAP1LC3A, SRC, BNIP3L, BECN1, and OPTN, across various cancer types, revealing significant differential expression patterns associated with molecular subtypes, stages, and patient outcomes." (PMID 39859167, 2025). "Notably, PRKN exhibited the highest alteration frequency, affecting 34% of all cancer samples, followed by OPTN (21%), PINK1 (18%), SRC (15%), BECN1 (13%), MAP1LC3A (9%), and BNIP3L (5%)." (PMID 39859167, 2025). "It inhibits cancer cell proliferation and migration by promoting ROS generation, inhibiting the PI3K/AKT signaling pathway, activating AMPK and regulating MAPK, and induces autophagic death of cancer cells by promoting autophagy-related proteins such as LC3-II and Beclin-1." (PMID 40917094, 2025).